FLCN (folliculin)
Diseases named in the same sentence as FLCN in open-access papers (continued):
Sharing a sentence is not in itself a finding about the gene and the disease.
tumor (continued). "FLCN dysfunction might lead to the development of various types of tumours other than renal tumours." (PMID 32190329, 2020). "FNIP1 and FNIP2 were also found to be critical for the tumor-suppressive function of FLCN in kidney tissue, suggesting that the appearance of tumors in BHD patients may be caused by the loss of essential FLCN-FNIP interactions." (PMID 32195250, 2020). "The tumor suppressor activity of FLCN is also supported by data from BHD animal models." (PMID 33137092, 2020). "Though it had been hypothesized FLCN protein had tumour suppressor properties and could be one of the major proteins regulating the mTOR pathway, only recently was FLCN established as a tumour suppressor gene that fits the classic two-hit model." (PMID 30326848, 2018). "The intragenic location of the FLCN mutation does not yet influence tumor screening strategies or treatment planning." (PMID 30586397, 2018). "Further experiments utilizing a FLCN construct harboring the germline mutation of this patient suggest that there may be some ability of FNIP1 and Tsc1 to compensate for one another in the chaperoning of the FLCN and Tsc2 tumor suppressors." (PMID 29774133, 2018). "In this case we demonstrate that this tumor is a sporadic renal AML as evidenced by somatic loss of Tsc1/2 protein in the tumor tissue compared to adjacent normal kidney without loss of FLCN protein expression." (PMID 29774133, 2018). "Interestingly, the truncated protein was still expressed both in cell culture and in tumor tissue, though it was strongly destabilized and its subcellular localization differed from wild-type FLCN." (PMID 28499369, 2017). "After stimulating with EGF ligand (20 ng ml−1) FLCN null cells (FTC-133 FLCN−/−) and cells expressing tumour-associated mutant forms of FLCN (FTC-133 K508R and FTC-133 dF157) have increased levels of phosphorylated EGFR (pEGFR) compared to cells expressing FLCN WT." (PMID 28656962, 2017). "FLCN has been shown to bind FNIP1, FNIP2, the Rag GTPases A and C/D, GABARAP and plakophilin-4 (refs 11, 12, 13, 14, 15, 16, 17, 18), but the biological significance of each of these interactions with regards to the tumour suppressor function of FLCN is under investigation." (PMID 28656962, 2017). "Reintroduction of wild-type FLCN, but not tumour-associated FLCN mutants, suppresses EGFR signalling in a Rab7A-dependent manner." (PMID 28656962, 2017). "Since a commercially available anti-FLCN antibody (CellSignaling, #3697) detected the overexpressed mutant protein in Western Blots, we decided to use this antibody to analyze the endogenous expression in patient tumor tissue." (PMID 28499369, 2017). "Afatinib significantly slowed the growth of FTC-133 (FLCN−/−) xenograft tumours compared to the Vehicle-treated tumours, suggesting that the increased pEGFR signalling observed in vitro is also important for in vivo growth of FLCN−/− tumours." (PMID 28656962, 2017). "Our results suggest that the tumour suppressor function of FLCN is, at least in part, due to its ability to inhibit the oncogenic signalling of EGFR, by acting as a GAP protein for Rab7A and therefore modulating the fate of receptor trafficking following endocytosis." (PMID 28656962, 2017). "Very little is known about the precise mechanisms of tumour suppression by human FLCN." (PMID 28656962, 2017). "Direct sequencing of exon 12 using genomic DNA obtained from the patient’s microdissected CCST cells (from the larger tumor) clearly revealed the loss of wild-type FCLN sequence, confirming the complete loss-of-function of the FLCN gene (Knudson’s 2-hit theory)." (PMID 27871249, 2016). "Interestingly, immunopositivity for folliculin was stronger in the cytoplasm of large tumor cells with bizarre nuclei than in that of the small tumor cells with round nuclei." (PMID 27871249, 2016). "Folliculin (FLCN), known for its role as a tumor suppressor, may play a crucial role in metabolic reprogramming of adipose tissue and shift to an oxidative phenotype." (PMID 28105413, 2016).
tumor (continued). "Somatic mutation analyses of FLCN, EGFR, and KRAS were also done in microdissected neoplasms." (PMID 26974543, 2016). "It is currently unknown whether synergism of EGFR/KRAS and FLCN LOH accelerates tumor progression in the lung." (PMID 26974543, 2016). "Our findings could provide insights into the therapeutic strategy for BHD renal tumorigenesis and other FLCN-mTOR related tumor growth." (PMID 26418749, 2015). "Currently, therapeutic approaches for BHD renal tumorigenesis and other mTOR-related FLCN-deficient neoplasia have not yet been described." (PMID 26418749, 2015). "Finally, ablation or restoration of FLCN in human cancer cells revealed tumor suppressor function in xenograft and soft agar assays." (PMID 24763318, 2014). "Strikingly, the majority of naturally occurring FLCN mutations predisposing to BHD are predicted to produce truncated proteins unable to bind AMPK, pointing to the critical role of this interaction in the tumor suppression mechanism." (PMID 24763318, 2014). "Together, our data suggest that FLCN is an evolutionarily conserved regulator of AMPK signaling that may act as a tumor suppressor by negatively regulating AMPK function." (PMID 24763318, 2014). "Clinical and genetic evidence suggest that FLCN acts as a tumor suppressor gene." (PMID 23874397, 2013). "Clinical and genetic evidence indicate that FLCN acts as a tumor suppressor gene." (PMID 23874397, 2013). "The reintroduction of tumor-associated FLCN mutants (FLCN ΔF157, FLCN 1–469 or FLCN K508R) fails to delay cell cycle progression in UOK257 cells." (PMID 23874397, 2013). "Importantly, FLCN protein levels are diminished in human ccRCC with VHL loss, further supporting a role for this tumor suppressor in the growth of ccRCC." (PMID 23922894, 2013). "Genetic evidence suggests that FLCN acts as a tumor suppressor gene." (PMID 23874397, 2013). "Here we provide evidence that WT, but not tumor-associated FLCN mutants, delay cell cycle progression through the late S and G2/M phase." (PMID 23874397, 2013). "We present here the crystal structure of folliculin carboxy-terminal domain and demonstrate that it is distantly related to differentially expressed in normal cells and neoplasia (DENN) domain proteins, a family of Rab guanine nucleotide exchange factors (GEFs)." (PMID 22977732, 2012). "We have also noted an inverse correlation between FLCN expression and mitochondria- and OXPHOS-associated genes across a variety of tumor types, most evident in tumors that possessed relatively low levels of FLCN and enrichment in mitochondria- and OXPHOS-associated gene expression." (PMID 21162720, 2010). "We investigated whether wild-type or mutant FLCN transgenes, or the endogenous mutant FLCN genes were lost during tumor progression." (PMID 20573232, 2010). "On the tumor level, the role of FLCN in CRCs in BHDS is largely unknown." (PMID 41193855, 2026). "GPNMB reactivity is non‐specific and cannot distinguish between FLCN‐mutated tumours and TFE3/TFEB RCCs, as well as various other TSC1/2/MTOR‐mutated tumours, but it may be diagnostically useful for screening for FLCN mutations that would help distinguish them from their mimics." (PMID 41384711, 2026). "If FLCN is the only altered gene in such a tumor, no mutation will be detected, which may imply that a non-neoplastic lesion was sampled." (PMID 40277780, 2025). "Unfortunately, the patient with the germline mutation did not have FLCN gene coverage on their somatic tumor NGS panel, meaning the VAF is unknown." (PMID 40277780, 2025). "Moreover, FLCN‐SD‐KI cells showed a greater capacity for tumor formation and faster growth, both of which could be abolished by rapamycin treatment." (PMID 37083230, 2023).
tumor (continued). "The expression level of endogenous Rab7A was the same across all of the different growth conditions (regular media, serum-free media or media without growth factors and amino acids) and was not affected by expression of FLCN WT or the tumour-associated mutants." (PMID 28656962, 2017). "Furthermore, we provided biochemical evidence indicating that FLCN WT protein, but not a tumour-associated missense FLCN mutant, increased the GTP hydrolytic activity of Rab7A." (PMID 28656962, 2017). "Thus we investigated if FLCN may exercise its tumor suppressing activity downstream from VHL by regulating LC3C or LC3B autophagy." (PMID 23922894, 2013). "It is not known whether tumours from patients carrying these truncating mutations, or from any other identified mutations, express endogenous mutated folliculin." (PMID 22977732, 2012). "Accordingly THBS1 regulation may be an important part of the tumor suppressor function of FLCN." (PMID 20573232, 2010). "For instance, recent studies have described a similar mechanism for mTORC1 regulation by folliculin, a regulator of the RAGC GTP-binding protein that converges with insulin signaling and mTORC1 regulation in tumor growth." (PMID 38396745, 2024). "FLCN as a tumor suppressor gene is a conserved negative regulator of AMPK, but the functional relationship between FLCN and AMPK is equivocal based on previous investigations on non-tumor cells using in vitro and in vivo systems." (PMID 34031471, 2021). "EGFR signalling is elevated in FLCN−/− tumours and the EGFR inhibitor afatinib suppresses the growth of human FLCN−/− cells as tumour xenografts." (PMID 28656962, 2017). "Thus, it also remains unclear how the FLCN–FNIP complex functions as a tumor suppressor." (PMID 28686218, 2017). "Analysis revealed that the tumor cells were immunopositive for vimentin, microphthalmia transcription factor, S100, CD1a, CD10, CD63, and folliculin, but immunonegative for cytokeratin, α-smooth muscle actin, HMB45, Melan-A, and PNL-2." (PMID 27871249, 2016). "To determine if there was a functional link between FLCN and the tumor-suppressing activity of VHL, we knocked down expression of FLCN in 786-O VHL(+) cells by using three different shRNAs." (PMID 23922894, 2013). "It is likely that the FLCN expression level in UOK257-3 cells is marginal for tumor suppression, allowing tumor growth in some animals but suppressing tumor growth in others." (PMID 20573232, 2010). "Administration of RIP‐12 inhibited the growth of IMR‐32 cell‐derived xenograft tumors, as evidenced by reduction in tumor volume, weight, and Ki‐67 proliferative activity, along with up‐regulation of NR1D1, RIOK3, FLCN, or FNIP1 as well as down‐regulation of LAMP1." (PMID 40899609, 2025). "Taking glutamine as an example, which is a key metabolic checkpoint between tumor cells and cDC1, while tumor cells compete for glutamine uptake through the SLC38A2 transporter, further impairing cDC1 function through the FLCN-TFEB signaling axis, thus inhibiting CD8+ T-cell killing activity." (PMID 41226585, 2025). "In contrast to RPTEC, global EGFR and MET activities showed less activity in the FLCN-negative UOK257 tumor cell line when compared with the FLCN-restored UOK257-2, even though EGFR and MET emerge as significantly important pathways in each cell model." (PMID 35863698, 2022). "Although Rab27B has been involved in tumor progression, metastasis, and drug resistance, the effect of FLCN-mediated regulation on its oncogenic activity is not known." (PMID 33981707, 2021). "This suggests that certain IFN response genes which strongly reduce proliferation form a deeper tumor suppressive layer protecting against uncontrolled proliferation in the absence of sufficient FLCN expression." (PMID 33459596, 2021).
tumor (continued). "The FLCN deletion activated the downstream signaling pathway, resulting in tumor formation rather than saving the deterioration of existing tumor cells." (PMID 32850947, 2020). "A document in the same year claimed that HIF1α increased in the lack of FLCN and promoted tumor growth." (PMID 32850947, 2020). "Studies in vitro suggest FLCN has a role facilitating mTOR activation at the lysosome surface, however further studies are needed to clarify mechanisms involved in mTOR signalling by the FLCN/FNIP complex and possibly validate the role of mTOR inhibition in tumour progression suppression." (PMID 30326848, 2018). "Our in vivo study demonstrated that inhibiting EGFR signalling with afatinib was sufficient to slow the growth of FLCN−/− tumours, but did not result in tumour regression." (PMID 28656962, 2017). "While array CGH on tumor material proved inconclusive on a 180 k standard array, FLCN MLPA analyses were consistent with deletion of the second FLCN allele in both tumor tissues (data not shown)." (PMID 28499369, 2017). "The observed effects of FLCN knockdown on tumor growth are consistent with the negative effect of FLCN overexpression on the formation of tumors by 786-O VHL(−) cells, as observed by others." (PMID 23922894, 2013). "Interestingly, FLCN, similarly to VHL, is necessary for the activity of LC3C-mediated autophagic program that we have previously characterized as contributing to the tumor suppressing activity of VHL." (PMID 23922894, 2013). "FLCN contributes to VHL-induced tumor suppression by a mechanism that does not appear to involve activation of the mTOR pathway." (PMID 23922894, 2013). "Though somatic mutations in FLCN occur in approximately 10 percent of sporadic tumors, we lacked the tissue required to determine the FLCN status in the tumor itself." (PMID 21162720, 2010). "Furthermore, the absence of FLCN expression in different tumor types was correlated with elevated expression of nuclear mitochondrial genes." (PMID 39201746, 2024). "EGFR expression and signalling is elevated in cells lacking the WT FLCN tumour suppressor." (PMID 28656962, 2017). "Interestingly, the tumour-associated mutant K508R displayed decreased Rab7A GAP activity and was not as effective as FLCN WT at stimulating GTP hydrolysis." (PMID 28656962, 2017). "The deregulation of mTOR activity found in the tumours of BHD animal models could be due to mTOR's general involvement in cancerous growth rather than a direct effect of FLCN's absence." (PMID 24910976, 2014). "Collectively, the analysis of the data suggests that FLCN functions as an evolutionarily conserved regulator of AMPK signaling, potentially acting as a tumor suppressor by exerting negative control over AMPK activity." (PMID 39201746, 2024). "For example, in the case of TFEB, non-canonical mTORC1 signaling is regulated by the Folliculin (FLCN) protein, a tumor suppressor that functions as a GTPase-activating protein (GAP) for the RagC/D GTPases." (PMID 39572689, 2024). "Our data indicate that a negative feedback loop constrains amino acid-induced, FLCN:FNIP2-mediated RagC activity in renal cells with constitutive mTORC1 signaling, and the resulting MiT/TFE hyperactivation may drive oncogenesis with loss of the TSC2 tumor suppressor." (PMID 36357396, 2022). "Although we saw a minor FLCN-dependent effect of MET inhibitors in RPTEC, these effects were not reproducible in BHD tumor cell lines UOK257 and FLCN reconstituted UOK257-2." (PMID 35863698, 2022). "We conclude that, in the absence of FLCN, TFE3 is constitutively active in renal epithelial cells, confirming TFE3 as a bona fide target of the FLCN tumor suppressor." (PMID 33459596, 2021). "The tumor suppressor FLCN, responsible for the Birt-Hogg Dubé renal neoplasia syndrome (BHD), is an AMPK-binding partner but the genetic and functional links between FLCN and AMPK have not been established." (PMID 24763318, 2014).
tumor (continued). "Thus, FLCN expression in DCs is required primarily for the activation and effector function of cytotoxic CD8+ T cells in the TME, but not for naive CD8+ T cell priming in the tumour dLNs or for cDC1 migration." (PMID 37407815, 2023).